IRAK2 (interleukin 1 receptor associated kinase 2)
Diseases named in the same sentence as IRAK2 in open-access papers (continued):
Sharing a sentence is not in itself a finding about the gene and the disease.
Sepsis (1 paper, 2020). Sepsis is defined as life-threatening organ dysfunction caused by a dysregulated host response to infection. "Correlation analysis showed that the expression of Irak2 was positively associated with NEAT1 in sepsis tissues." (PMID 32414769, 2020). "In conclusion, our research demonstrated that NEAT1 silencing obstructed sepsis progression by decreasing the expression of Irak2 by sponging miR-370-3p." (PMID 32414769, 2020). "Taken together, these results suggest that upregulation of Irak2 transposed the NEAT1 silencing-mediated suppressive effect onto sepsis progression." (PMID 32414769, 2020). "Further research indicated that downregulation of miR-370-3p or upregulation of Irak2 rescued NEAT1 silencing-mediated inhibitory effect on sepsis progression." (PMID 32414769, 2020). "Knockdown of NEAT1 hampered sepsis progression by downregulating Irak2 via interacting with miR-370-3p in LPS-induced RAW 264.7 and HL-1 cells." (PMID 32414769, 2020). "To deeply understand the regulatory mechanism of miR-370-3p in sepsis, we found its target gene, Irak2, which was correlated with LPS-induced inflammation injury." (PMID 32414769, 2020). "In this research, the mRNA and protein levels of Irak2 were clearly elevated in sepsis tissues and LPS-induced RAW 264.7 and HL-1 cells." (PMID 32414769, 2020). "Next, we checked the expression of Irak2 and the data indicated that Irak2 was clearly increased in sepsis tissues and LPS-induced RAW 264.7 and HL-1 cells." (PMID 32414769, 2020). "NEAT1 and Irak2 were upregulated in sepsis tissues and LPS-induced RAW 264.7 and HL-1 cells, opposite to the expression of miR-370-3p." (PMID 32414769, 2020). "Further research demonstrated that overexpression of Irak2 transposed the repressive impact of NEAT1 silencing on sepsis progression." (PMID 32414769, 2020). "All in all, our results suggest that NEAT1 might serve as a sponge, interacting with and downregulating miR-370-3p, thus altering the expression of Irak2, eventually mediating the progression of sepsis in LPS-induced RAW 264.7 and HL-1 cells." (PMID 32414769, 2020). "Therefore, Irak2 may be an attractive drug target for sepsis and new regulators regulating Irak2 need to be determined." (PMID 32414769, 2020). "The NEAT1/miR-370-3p/Irak2 axis might contribute to improvements in the treatment of sepsis." (PMID 32414769, 2020). "To study the relationship between Irak2 and NEAT1 in sepsis progression, we first transfected LPS-induced RAW 264.7 and HL-1 cells using pcDNA-Irak2 or pc-DNA-control." (PMID 32414769, 2020).
Splenomegaly (1 paper, 2016). Abnormal increased size of the spleen. "ABIN1[D485N] × IRAK2[E525A] mice still displayed splenomegaly and increased levels of autoantibodies and other Igs at 6 mo of age, similar to ABIN1[D485N] mice." (PMID 27807192, 2016).
Stroke (1 paper, 2023). Sudden impairment of blood flow to a part of the brain due to occlusion or rupture of an artery to the brain. "RT–qPCR and Western blot methods confirmed significant changes in the expression levels of Aplnr, Cdkn1a, Irak2, and Serpine1 after MCAO, which may serve as therapeutic targets to prevent cardiovascular complications after stroke." (PMID 37965346, 2023).
tumor (16 papers, 2008 to 2024). "We conducted Gene Ontology (GO) analysis to explore the biological function of IRAK2 and performed a case analysis to define its clinical role in mediating tumor response to radiotherapy." (PMID 37108068, 2023). "We evaluated the impact of IRAK2 downregulation on cell phenotype, proliferation, sphere-forming ability and tumour development." (PMID 36768848, 2023). "In vivo, mice inoculated with the cell line overexpressing IRAK2 had significantly reduced tumor growth at baseline and in response to RT (50 Gy/10 fractions) compared to mice implanted with the parental radioresistant cell line (low IRAK2)." (PMID 37112730, 2023). "The present study conducted GO analysis to explore the biological function of IRAK2 and performed a case analysis to define its clinical role in disease progression and mediating tumor response to RT." (PMID 37108068, 2023). "IRAK2 has also been found to be expressed in triple-negative breast cancer cells, and its downregulation decreases tumor growth." (PMID 37108068, 2023). "The increased expressions of cleaved caspase-8 and cleaved caspase-3 were further confirmed by immunofluorescence staining and western blotting on tumor tissues in IRAK2-overexpressed xenografted mice treated with RT." (PMID 34249686, 2021). "IRAK2-overexpressed xenografts demonstrated an apparent reduction in tumor volume when compared with the control." (PMID 34249686, 2021). "After exposure to RT, the tumor volume of IRAK2-overexpressed mice was statistically significantly decreased when compared with that of control ones, implicating that IRAK2 enhances the efficacy of IR treatment in radioresistant tumors." (PMID 34249686, 2021). "IRAK2 overexpression alone inhibited tumor growth, indicating that IRAK2 may function as a tumor suppressor." (PMID 34249686, 2021). "Finally, only one of these candidates corresponding to IRAK2 showed cytoprotective activity in several additional tumor cell lines (ALVA31, A549, U251, HeLa) treated with CDDO-Im." (PMID 23724040, 2013). "We concluded that although IRAK2 downregulation affected the molecular pathways in the cell lines considered in this study slightly differently, overall, its downregulation was advantageous because it decreased cellular growth in vitro and delayed tumour progression in vivo." (PMID 36768848, 2023). "For instance, IRAK4 rs4251545 was associated with a 2.56-fold increase in invasive disease (OR = 2.56; 95% CI = 1.1–5.91); whereas, inheritance of the IRAK2 rs242724 minor alleles were linked to non-aggressive disease (i.e., tumor size <2 cm, ER + /PR + /Her-2 neu+ status)." (PMID 24194738, 2013). "Immunohistochemical staining showed IRAK2 expression in the cytoplasm and membrane of OSCC tumor samples." (PMID 34249686, 2021). "Our high resolution copy number analysis outlined that CNA genes positioned nearest to VHL (16/48 tumour cases) were differentially lost 60kb downstream in 29 ccRCC tumour cases (FANCD 2), but 30kb upstream only in 17 ccRCC tumour cases (IRAK2)." (PMID 28486536, 2017). "Of the 4 IRAK2-targeting siRNAs tested, 3 rescued against CDDO-Im-induced cell death in multiple tumor cell lines." (PMID 23724040, 2013). "Our data indicated that IRAK2 is an attractive target, in both predictive and therapeutic aspects, for radioresistant OSCC because the overexpression of IRAK2 may contribute to enhanced/restore IR-induced tumor cell killing." (PMID 34249686, 2021).
cancer (12 papers, 2013 to 2023). A tumor composed of atypical neoplastic, often pleomorphic cells that invade other tissues. "Other protein kinases, such as checkpoint kinase (Chk1) and Interleukin-1 Receptor Associated Kinase 2 (IRAK2), can reduce protein levels of phosphorylated Smurf1 at Thr145, Thr161, and Thr682 compared to its basic expression in cancers." (PMID 33718111, 2020). "IRAK2 has been implicated in playing several roles in human cancers." (PMID 37108068, 2023). "Interleukin 1 receptor associated kinase 2 (Irak2) was involved in many human cancers." (PMID 32414769, 2020). "GO analysis identified that IRAK2 is tightly correlated with 10 of the top 14 enriched biological processes; this finding suggests it is closely related to cancer immunity and demonstrates the significant role of IRAK2 in the cellular response to irradiation." (PMID 37108068, 2023). "Cancer cell growth, migration, tumourigenesis and chemoresistance can all be impacted by targeting the proteins involved in the IRAK2 pathway, including IRAK1 and IRAK4." (PMID 36768848, 2023). "Except for SKCM (n = 457, p < 0.001), IRAK2 played a detrimental role in five different cancer types, which contained LGG (n = 524, p < 0.001), LIHC (n = 368, p = 0.023), LUAD (n = 513, p = 0.031), MESO (n = 84, p = 0.008), and PAAD (n = 177, p = 0.010)." (PMID 35211171, 2022). "To verify these results by another method, we generated cancer cell lines in which IRAK2 expression was stably knocked-down in PPC1 cells using recombinant IRAK2-targeting shRNA lentiviruses and compared them to cells harboring scrambled shRNA control vectors." (PMID 23724040, 2013). "Recently, the role of IRAK2 has been investigated in various cancers." (PMID 37108068, 2023). "Overall, IRAK2 downregulation decreased cellular aggressive growth and pathways often exploited by cancer cells to endure stress; therefore, IRAK2 may be considered an interesting target to compromise TNBC progression." (PMID 36768848, 2023). "IRAK2 may facilitate the process of radiation immunity by inducing cancer cells to undergo apoptosis." (PMID 34249686, 2021). "IRAK2 and IRAK4 were moderately expressed, and IRAK3 expression was the relatively lowest in pan-cancer." (PMID 35211171, 2022). "IRAK2 silencing also decreased the expression of cleaved caspase-8 and -3 in both two types of OSCC cancer cells when compared with their control cells." (PMID 34249686, 2021). "It has been demonstrated that microRNA-146a can target many genes, such as IRAK1, IRAK2, TRAF6, RIG-I, IRF-5, STAT-1, PTC1, Numb, and WASF2, to play a variety of roles in human diseases, including cancers and inflammatory immune diseases." (PMID 31798643, 2019). "Moreover, IRAK2 downregulation compromised ERN1 signalling and autophagy, which are pathways that are frequently exploited by cancer cells to survive, further supporting the beneficial impact of IRAK2 downregulation in TNBC." (PMID 36768848, 2023). "Furthermore, differentially expression of IRAK2 and MECOM genes has been reported in many studies in cancers or COPD." (PMID 36194576, 2022). "In addition, we also found that the presence of HDAC7 led to the upregulation of genes related to immune processes (IL16, FCGR2A, IRAK2, CD86 and CD40, among others) and cancer (RASSF4, RAB31, NEDD9 and RASSF2, among others)." (PMID 25675295, 2015). "Also, IRAK2, IRAK3, and IRAK4 were higher expressed in the C6 subtype in pan-cancer." (PMID 35211171, 2022).
infection (12 papers, 2009 to 2022). The state of being infected such as from the introduction of a foreign agent such as serum, vaccine, antigenic substance or organism. "This is not surprising because these analyses were done in classical inbred mice, which have different levels of pathology but similar IRAK-2 alleles, thus precluding the assessment of the wild-derived IRAK-2 allele in T cell activation during infection." (PMID 21998578, 2011). "However, significant alterations in the expression pattern of specific target genes (TRAF6, IRAK1 and IRAK2) were observed only after 32 hours of infection." (PMID 25083878, 2014). "Significantly, our results showed that the expression of six major adaptor molecules (Myd88, IRAK2, IRAK4, TRAF3, TBK-1 and IRF7) downstream of RNA sensors were dramatically decreased in the PAMs with a PRRSV-ADE infection." (PMID 36680075, 2022). "Infection with the IRAK-2-specific hairpin led to a specific decrease in IL-17 expression, which strongly suggests that IRAK-2 is involved in transcriptional up-regulation of IL-17." (PMID 21998578, 2011). "Interestingly, silencing IRAK2 and NIK reduced virus replication as indicated by lower luciferase activity, suggesting an infection-promoting role for these two kinases." (PMID 28480889, 2017). "As would be expected, TRAF6 and IRAK1 were decreased in LV-Omp25-infected cells compared to the cells infected with LV-Blank 24 h post-infection, with no change for IRAK2." (PMID 29387067, 2017). "After 7 weeks of infection, the SEA/CFA-immunized IRAK-2-/- mice appeared healthier and exhibited significantly reduced granulomatous inflammation when compared to similarly treated WT BL/6 mice and IRAK-2+/- littermate controls." (PMID 21998578, 2011). "In the case of infection with the susceptible strains, besides the increased methylation level of Traf6 gene and hypomethylation of Irak-2 gene, normal methylation of the other tested genes related to the TLR signaling pathway was observed, which may induce effective responses to infection." (PMID 32605029, 2020).
metabolic disorders (1 paper, 2023). "Importantly, defects in Irak2 or its kinase, in addition to demonstrating that translocation of Irak2 into the mitochondrial membrane space and inner membrane plays a role, also reduced HFD-induced metabolic disorders." (PMID 38072993, 2023).
IRAK2 also shares sentences with these, for which no sentence is quoted: Alzheimer disease (2 papers); Obesity (2); acne (1); atherosclerosis (1); bacterial infections (1); breast tumours (1); eczema (1); esophageal carcinoma (1); hepatocellular carcinoma (1); Hypercalcemia (1); influenza (1); Insulin resistance (1); intracerebral hemorrhage (1); latent infection (1); leukemia (1); liver fibrosis (1); lung adenocarcinoma (1); lung squamous cell carcinoma (1); measles (1); medulloblastoma (1); myocardial inflammation (1); pertussis (1); pheochromocytoma (1); pneumonia (1); prostate adenocarcinoma (1); rectum adenocarcinoma (1); respiratory diseases (1); retinal angiomas (1); rheumatoid arthritis (1); stomach adenocarcinoma (1).
A further 2 diseases each share a sentence with IRAK2 in 1 paper.